RNU6-772P (RNA, U6 small nuclear 772, pseudogene)
Gene: Small nuclear RNA gene on chromosome 21 (20,355,748 to 20,355,852, reverse strand). Ensembl gene ENSG00000251851.
Homologues: Orthologues: chimpanzee U6 (94% identical), macaque U6 (94% identical), pig U6 (72% identical), rabbit U6 (64% identical). Paralogues in human: RNU6-211P (81% identical), RNU6-310P (80% identical), RNU6-768P (80% identical), RNU6-1152P (79% identical), RNU6-1263P (78% identical), RNU6-1289P (78% identical), RNU6-552P (78% identical), RNU6-574P (78% identical), RNU6-686P (78% identical), RNU6-117P (77% identical), RNU6-1190P (77% identical), RNU6-289P (77% identical), and 1287 more.